IL6 (interleukin 6)
Diseases named in the same sentence as IL6 in open-access papers (continued):
Sharing a sentence is not in itself a finding about the gene and the disease.
COVID-19 (continued). "Here, we have demonstrated that IL-6 exerts prothrombotic effects on human endothelial cells because it promotes expression of functional TF, suggesting that this might be one of the possible mechanisms by which COVID-19 causes thrombosis." (PMID 35050236, 2022). "COVID-19-associated inflammation has been linked to a reduced expression of many selenoproteins, including glutathione peroxidase, thioredoxin reductase and those involved in controlling endoplasmic reticulum (ER) stress and the expression of interleukin-6 (IL-6) in SARS-CoV-2 infected cells." (PMID 35204134, 2022). "Additionally, COVID-19 causes a cytokine storm linked with a rise in IL6 levels." (PMID 35039779, 2022). "Finally, our results suggest that serum levels of IL-6 may represent a promising marker of unfavorable outcomes associated with PDM in COVID-19 patients." (PMID 35898449, 2022). "COVID-19-associated severe infections are largely mediated by a cytokine storm, defined as a systemic inflammatory response with the excessive activation of immune cells and proinflammatory mediators such as FN-α, IL-1β, and IL-6 that lead to lung injury, then respiratory failure and death." (PMID 35456120, 2022). "The effect of demographic factors on IL6 levels and SARS-CoV-2 viremia was also assessed." (PMID 35783606, 2022). "Therefore, in the current pilot study, we quantified the concentration of IL-26 in plasma samples from patients with acute COVID-19 (COVID-19 group), compared with healthy control subjects (Control group), and analyzed its association with the neutrophil-mobilizing cytokines IL-6, IL-8, and TNFα." (PMID 36466824, 2022). "A retrospective multicenter study of 68 COVID-19 noted 27 deaths that could be attributed to myocardial damage and/or circulatory failure as one of the primary causes of mortality, with elevated C-reactive protein and IL-6 levels linked to higher mortality." (PMID 35336888, 2022). "In addition, IL-6 can also aggravate the damage to systemic organ function by inducing apoptosis of lymphocytes and participating in coagulation dysfunction associated with COVID-19." (PMID 36380355, 2022). "While inflammatory cytokines such as IL-6 could underpin some of the long-term neuropsychiatric features of COVID-19, persistently elevated levels of IL-6 and other cytokines may be a hallmark of post-acute sequelae of COVID-19." (PMID 35741183, 2022). "This study assessed the relationship between IL6 and SARS-CoV-2 viremia." (PMID 35783606, 2022). "Nevertheless, a meta-analysis with direct systematic comparisons of COVID-19 with other critical illnesses associated with elevated cytokine concentrations (n = 1245) reported that in patients with severe or critical COVID-19, the pooled mean serum IL-6 concentration was 36.7 pg/mL." (PMID 35053224, 2022). "It is assumed that the underlying mechanisms in COVID-19, such as acute respiratory distress syndrome, extensive lung damage, and cytokine release storm, such as IL-1, IL-6, and TNF-α leading to interstitial pulmonary inflammation, could have impacts on these autoimmune disorders." (PMID 35495619, 2022). "For example, serum Fe3+ concentration is inversely correlated with COVID-19 severity both before and after treatment, predicts the progression from mild and moderate to severe and critical illness, and is associated with the elevation of the inflammatory cytokine IL-6." (PMID 36016660, 2022). "Moreover, a previous study of our group showed that high levels of IL6 (above 30 pg/ml) were associated with worse prognosis of COVID-19, and also with a better response to tocilizumab, thereby suggesting a role of IL6 levels in guiding treatment and predicting response to this therapeutic agent." (PMID 35783606, 2022).
COVID-19 (continued). "However, when analyzed according to the time from disease onset, the IL-6 elevation was found only at the late stage of severe COVID-19 while IL-10 and IL-1RA levels were significantly associated with disease severity and patients’ outcomes already at the first week after symptom onset." (PMID 35887283, 2022). "Besides, recent studies suggest that excessive production of some cytokines, such as IL-6 may be the leading cause of inflammatory response in COVID-19." (PMID 35619180, 2022). "IL-6 is the canonical regulator the acute phase response, well established to control hepcidin and serum iron levels (Nemethet al., 2004) and has been previously reported to associate with serum iron in COVID-19 (Hippchenet al., 2020;Lvet al., 2021;Moreiraet al., 2021)." (PMID 35935705, 2022). "Overall, elevated expression of serum IL-6 is associated with adverse clinical outcomes and mortality in COVID-19 patients, and the IL-6 receptor antagonists such as tocilizumab may reduce 28-day all-cause mortality in hospitalized patients with COVID-19." (PMID 35248063, 2022). "Moreover, inflammatory cytokines-TNF-α and IL-6, which may initiate mitochondrial ROS production and are associated with ATP production, were found in COVID-19 serum." (PMID 35281470, 2022). "However, certain diseases, like in COVID-19, may cause misregulation of the NF-κB signaling, causing overproduction of IL-6 and other cytokines in a cytokine release syndrome (CRS)." (PMID 35197994, 2022). "Furthermore, COVID-19 dysbiosis causes an increase in inflammatory cytokines such as IL-6, TNF-α, and IL-1β, which might be one of the important predisposing factors for severe infection." (PMID 36532032, 2022). "IL-6 may be a prospective target cytokine to treat COVID-19-associated ARDS." (PMID 36263178, 2022). "Important data also show that the increase in IL-6 in COVID-19 may be associated with poor prognosis, admission to the Intensive Care Unit, Acute Respiratory Distress Syndrome, respiratory failure, shock, multiple organ dysfunction, and risk of death, being a good marker to monitor these patients." (PMID 36295080, 2022). "Furthermore, elevated IL-6 levels are associated with poor COVID-19 patient prognosis." (PMID 35562935, 2022). "IL-6 and IL-1 blockade may be associated with clinical improvement in patients with COVID-19." (PMID 35185562, 2022). "The steady states il6 macrophages are only found when there is EGFR_e in the microenvironment and may correspond to inflammatory pathogenic states as those seen in cancer and severe COVID-19." (PMID 35480895, 2022). "Using the data presented here on IgM SARS-CoV-2 peptide reactivity and serum cytokine levels of IL-1α, IL-6, and IL-18, we have identified a unique biomarker panel which could be used for early identification of COVID-19 patients with increased risk of severe and potentially fatal disease." (PMID 35386707, 2022). "The NIC-hLYS particles exhibited suppression of the inflammatory cytokines TNF-α and IL-6, which have been implicated in the development of more severe COVID-19, while elevating the production of the inflammatory cytokine IL-1β, which may contribute to enhanced antiviral activity." (PMID 33571320, 2021). "Furthermore, vitamin C may control the cytokine storm, which is characterized by elevated levels of the pro-inflammatory cytokine IL-6, increasing the risk of respiratory failure necessitating mechanical ventilation in COVID-19 patients." (PMID 34884440, 2021). "By analyzing the correlations between IL-6 levels and health conditions, underlying diseases, several key laboratory detection indices, and the prognosis of 1,473 patients with the coronavirus disease 2019 (COVID-19), the role of IL-6 during SARS-CoV-2 infection was demonstrated." (PMID 33746945, 2021).
COVID-19 (continued). "Our findings suggest that discharged patients continue to recover from the physiological effects of COVID-19, and the association of IL-4, IL-6, and IL-10 levels with metabolic changes and liver function repair may have important implications for clinical manifestations and treatment of COVID-19." (PMID 34307393, 2021). "Therefore, it is suggested that LHQW may regulate CS by inhibiting IL6, controlling the immunological stress caused by COVID-19, and relieving inflammatory symptoms caused by pulmonary infection." (PMID 34731090, 2021). "Thus, if the severity of COVID-19 correlates with the amount of IL-6, patients with severe course may be at greater risk of developing post-COVID depression." (PMID 34575258, 2021). "Suggesting that this may also be the case in COVID-19, significant positive associations have been reported between plasma concentrations of IL-6 and the frequency/absolute number of CD10-CD64+Lox1+ and CD16low/highCD10- neutrophils as well as CD16IntCD44LowCD11bInt LDIBs." (PMID 34149717, 2021). "IL-6 inhibitors, such as tocilizumab (monoclonal antibodies), inhibit the IL-6 transduction pathway and may represent a potential therapeutic choice for the COVID-19 associated with an exaggerated inflammatory response." (PMID 33714258, 2021). "According to the dysregulation of host immune responses in the development of cytokine release syndrome (CRS) as pathologic keystone for disease evolution of Covid‐19, inhibition of IL‐6 may be a novel target for therapeutics in patients with Covid‐19." (PMID 34059065, 2021). "It has been suggested that the COVID-19-related cause of death may be induced by a specific “cytokine storm” with an elevated level of cytokines, (especially IL-1 and IL-6, systemic inflammatory response syndrome—SIRS) leading to multiple organ failure with high mortality." (PMID 34685427, 2021). "With a clear association between obesity and IL-6 levels evident, it is probable that genetic factors influencing weight gain would also have a corresponding effect on IL-6 and may become a risk factor for COVID-19 patients." (PMID 34452063, 2021). "The mechanism underlying the elevated COVID-19 mortality in patients with diabetes may be explained by the increase in chronic inflammatory markers, such as C reactive protein, interleukin 6, interleukin 10, and tumor necrosis factor-α, which promote susceptibility to COVID-19." (PMID 34940517, 2021). "Unabated angiotensin II activity may also be in part responsible for endothelial dysfunction and COVID-19-associated organ injury through promoting microvascular thrombosis, coagulopathy, inflammation, hypofibrinolysis, interleukin-6 (IL-6) production, and ROS production." (PMID 34066226, 2021). "Furthermore, IL-6 levels are elevated in patients with COVID-19 and are associated with a poor prognosis, and are further increased in severe COVID-19 associated symptoms compared to mild patients, suggesting the importance of this cytokine as a marker to monitor disease progression and development." (PMID 34276659, 2021). "Use of anticytokine therapies, such as tocilizumab (anti-IL-6) has been suggested by some studies as a promising treatment, which may be capable of reducing the risk of invasive mechanical ventilation and death in patients with severe COVID-19." (PMID 34535189, 2021). "Furthermore, SPM reduce the production of pro-inflammatory cytokines, including those involved in SARS-Cov-2 such as IL-6 and IL-1β." (PMID 34437568, 2021). "In addition, our data suggested that lymphocytopenia, and increased levels of hsCRP, D-dimer, LDH, IL-6, and IL-10 were associated with severity and disease course of COVID-19 and might indicate a poor therapeutic efficacy." (PMID 33811756, 2021). "IL-6 may cause damage to lipids, proteins and DNA by increasing oxidative stress, which, as a consequence, leads to an impairment of the body’s structure and function and causes the rapid progression of COVID-19 in patients with diabetes." (PMID 34299225, 2021).
COVID-19 (continued). "Albeit indirect, another possible mechanism, which could explain the association between periodontal disease and a severe COVID-19 course, could be the overproduction of phlogistic molecules, such as IL-6 and IL-17, in healthy patients and patients with chronic diseases such as diabetes." (PMID 33975613, 2021). "Given the stability over time of those mediators most closely associated with disease severity (including IL-6 and GM-CSF), we hypothesized that differences in plasma mediator levels between patients with severe and moderate COVID-19 would be apparent early in the course of disease." (PMID 33692097, 2021). "A severe COVID-19 inflammatory response contributes to a pro-NETosis state, so the potential therapies targeting NETosis (e.g., disulfiram, colchicine, dornase alfa, IL-1 receptor antagonists, anti-IL-6 etc.)potentially could decrease the risk of COVID-19 complications." (PMID 34578460, 2021). "We hypothesize that the engagement of the glucocorticoid receptor by dexamethasone in these co-expressing cell types reduces local and systemic IL-6 production, which in turn restores immune homeostasis and mitigates the progression of the COVID-19 associated acute respiratory distress syndrome." (PMID 33723251, 2021). "Additionally, we were able to identify several factors that were considered effect modifiers on the efficacy of IL-6 (receptor) antagonists in COVID-19 patients: clinical setting (ICU), baseline risk of mortality, use of glucocorticoids and use of azithromycin." (PMID 34728658, 2021). "These lines of evidence may suggest that respiratory failure among COVID-19 patients is associated with changes in cytokine profiles, such as over-production of IL-6 and CRP, which can be intensified during the second and mainly the third trimesters of gestation." (PMID 34765620, 2021). "Careful patient selection and timing for IL-6 (receptor) antagonist treatment in COVID-19 patients is crucial, especially considering the increased risk of side effects—neutropenia, impaired liver function and secondary infections—when IL-6 (receptor) antagonists were used." (PMID 34728658, 2021). "This review also confirms that certain laboratory tests that are part of routine care have also been reliably associated with severe and fatal cases of COVID-19, and including serum IL-6 could be relevant for prognosis but could also improve therapeutic decision making." (PMID 34185801, 2021). "This was accompanied by an increased trend of systemic IL-10 and IL-6, as well as a dysregulated serum lipid response dominated by polyunsaturated fatty acid-containing phosphatidylethanolamine, recapitulating cytokine and lipid responses associated with severe human COVID-19." (PMID 34159329, 2021). "It should be noted that proinflammatory cytokines such as TNF-α, IL6, and IL1β may promote the disruption of lipid metabolism resulting in systemic inflammation, and that COVID-19 itself has been associated with dyslipidemia, which may worsen obesity-associated dyslipidemia." (PMID 34281182, 2021). "Genetically mimicking IL6R blockade using genetic instruments from the IL6R gene strongly associated with c-reactive protein was associated with lower risk of hospitalized COVID-19, but whether these associations are due to IL-6, IL-6R, or pleiotropic effects via other mechanisms is unclear." (PMID 34163532, 2021). "Thus, monitoring the levels of multiple cytokines, especially IL-6, IL-8, and IL-10, during the early stages of COVID-19 may help to identify patients who have the greatest risk for development of ARDS." (PMID 34088317, 2021). "Moreover, there is some evidence that genetic variants in the IL-6 inflammatory pathway may be associated with life-threatening disease supporting the therapeutic strategy of IL-6 inhibition in severe COVID-19 cases." (PMID 34506608, 2021).
COVID-19 (continued). "To further validate the findings, as disease severity progresses in patients with COVID-19, we detected a concomitant rise in serum cytokine levels associating immune cell communication, such as IL6, IL10, IGF1, and GALECTIN-1, may play roles on reduction and exhaustion of T cell populations." (PMID 34238338, 2021). "Increasing IL-10, Th1 suppression, and suppression of IL-6 level by tocilizumab used during the cytokine storm period increase the risk of invasive pulmonary aspergillosis, which progresses with a cavity and has a very poor prognosis in the follow-up period in COVID-19 patients." (PMID 34284532, 2021). "Therefore, vitamin D deficiency provides a risk factor for elevated IL-6 levels, and in turn, could be used as an indicator of potential severe respiratory symptoms in COVID-19 patients." (PMID 34452063, 2021). "Our results showed that IL-6 (receptor) antagonists were associated with a reduction in mortality, a reduction in mechanical ventilation and a reduction in the composite endpoint of mortality and mechanical ventilation for COVID-19 patients based on moderate to high certainty evidence." (PMID 34728658, 2021). "In addition, PTGIS possesses anti-inflammatory properties by modulating the expression of interleukin-1 (IL-1), IL-6, and IL-10, which may be associated with COVID-19 severity." (PMID 34315889, 2021). "Therefore, the level of circulating IL-6 may be a risk predictor of cardiovascular events in COVID-19." (PMID 33995078, 2021). "Direct correlations between COVID-19 outcomes and individual cytokines and immune cell populations indicate symptoms of COVID-19 are associated with elevations in interleukin 1 beta (IL-1β), IL-6, interleukin 10 (IL-10), and TNFα), as well as a general lymphopenia." (PMID 33967944, 2021). "Elevated levels of blood markers such as lactate dehydrogenase, D-dimers, procalcitonin, serum ferritin, and interleukin-6, as well as leucopoenia, were also found to be associated with worse COVID-19 outcomes, and therefore could potentially be used to monitor disease prognosis." (PMID 34006330, 2021). "However, the mild and severe COVID-19 groups showed different patterns of IL-6 polymorphisms." (PMID 34634929, 2021). "Elevated CRP, D-Dimer, and interleukin-6 were seen in all three, high ferritin levels in both the strong and the weak, and low lymphocyte counts in the strong and the contributive, whereas high NT-proBNP levels in the contributive and the strong COVID-19-association mortality categories." (PMID 34510338, 2021). "In patients who are severely ill with COVID-19, the glycosylation of anti-spike IgG is changed, which can lead to pathology by over-activation of IgG effector functions, as we show here by particularly amplifying the production of COVID-19-associated cytokines such as IL-6 and TNF." (PMID 33979301, 2021). "Therefore, there is a correlation among elevated acute phase reactants—such as fibrinogen, CRP, and IL-6—which may contribute to COVID-19-associated hypercoagulability." (PMID 33670394, 2021). "Indeed, patients with COVID-19 and vitamin D deficiency have been shown to exhibit significantly higher serum level of several inflammatory and coagulation biomarkers such as C-reactive protein, IL-6, TNF-α, ferritin, fibrinogen and D-dimer." (PMID 33906375, 2021). "In conclusion, ferritin, D-dimer, CRP, NLR, cytokines (IL-6, IL-18, and IL-10), and cytokine receptors (IL-1Ra and sIL-2rα [sCD25]) in combination with clinical information may aid the early identification of patients at risk of critical COVID-19." (PMID 34422145, 2021). "Although the effects of exercise training-secreted IL-6 on immune response modulation are well reported, more data are needed in humans for a set of severe inflammatory diseases in order to ensure the safe practice of exercise to mitigate or to treat patients at risk of developing severe COVID-19." (PMID 33613573, 2021).